TNF (tumor necrosis factor)
Diseases named in the same sentence as TNF in open-access papers (continued):
Sharing a sentence is not in itself a finding about the gene and the disease.
infection (continued). "More importantly, anti-N titers reflecting infection were positive at visit three in two subjects from each group (HC, non-anti-TNFα and anti-TNFα)." (PMID 35893835, 2022). "However, the expression profile of TNF-α, IFN-α, IL-6, IL-12 and RANTES 6 h post-infection was similar for both C1q-treated H1N1 and H3N2 subtypes." (PMID 35328462, 2022). "In the context of host immune response, ‘classically activated’ M1 Mφs, typically induced by lipopolysaccharide (LPS), interferon (IFN)-γ, or tumor necrosis factor (TNF), provide rapid “first-line” defense upon infection by direct engulfment and elimination of pathogens in peripheral tissues." (PMID 35565395, 2022). "Like the other NF-κB inhibitors, protein C2 and F3 are expressed early during infection and are non-essential for virus replication, but function within the cytosol to block the pathway downstream of receptors for TNFα and IL- 1β." (PMID 36301238, 2022). "Furthermore, the induction of IL-6, IL-23, IL-1β and TNFα by IL-17 constitutes a positive feedback loop that enhances their production by Th17 cells production and strengthens the effects of IL-17 which may form the basis of a self-sustaining process for IL-17 secretion during infection." (PMID 36136963, 2022). "Infection by SARS-CoV-2 in rare severe cases triggers an intense and rapid innate immune response (the cytokine storm) that leads to the release of proinflammatory and procoagulant cytokines (interleukins, tumor necrosis factor-alpha, interferons)." (PMID 35337362, 2022). "Infection-induced OXSR1 may suppress protective NLRP3 inflammasome responses and downstream IL-1β/TNF-α production." (PMID 35545295, 2022). "Here, we demonstrated that Att-S74-T3Bo infection induces alterations in innate immune myeloid and lymphoid cells in peripheral blood, eliciting significant levels of the pro-inflammatory cytokines TNFα, CXCL10, and IFNγ in sera as early as 3 days post-infection." (PMID 36466866, 2022). "In conclusion, anti-TNF-α de-escalation does not seem to reduce infections or skin manifestations in patients on standard-dosed anti-TNF-α treatment; however, the available evidence is of low quality." (PMID 35625771, 2022). "Similarly, the expression of the proinflammatory cytokines IL-1β, IL-6, and TNF-α was induced by H7N9 infection, but decreased in response to pdmH1N1 infection." (PMID 35269402, 2022). "qPCR showed that IQGAP1 depletion prevented the upregulation of IL-6 and TNF-α induced by infection with the WT strains but did not affect IL-6 and TNF-α expression in the ΔompA strain-infected groups." (PMID 35844614, 2022). "Basic studies have suggested that various proinflammatory cytokines, such as tumor necrosis factor-alpha (TNF-α) and receptor activator of NF-κB ligand (RANKL), which are released during infection, may promote the development and activity of osteoclasts." (PMID 35596169, 2022). "Remarkably, deletion of both tie1 and tie2 in a Δvprh/Δhns1 background (Δvprh/Δhns1/Δtie1/Δtie2) completely abolished the cell death and IL-1β secretion observed upon infection of BMDMs with the Δvprh/Δhns1 strain, without affecting TNFα secretion." (PMID 36155655, 2022). "Therefore, it is possible that during HZ, the infection of VZV induces T cell-mediated immune response, then these VZV-specific T cells infiltrate into ganglia, stimulated by VZV antigens, and secrete TNF-α to induce pain in patients with PHN." (PMID 35720399, 2022). "In addition, ASFV-ΔH240R infection induced higher expression of proinflammatory cytokines, including IL-1β, IL-6, TNF-α, and C-X-C motif chemokine ligand 8, in PAMs than did ASFV-WT infection." (PMID 36326277, 2022). "TNF, IL-17, MAPK and NF-kB signaling pathways may play key roles in the immunopathogenesis mechanism at all stages of infection." (PMID 35573776, 2022). "Notably, we observed rapid up-regulation of IL-17, TNF and TLR signaling pathways, indicating treatment measures should be taken in the early stage after infection." (PMID 35565570, 2022).
infection (continued). "A central role in clearing PCV2 infection could be actually played by PCV2-specific, IFN-γ/TNF-α co-secreting CD4+ cells after vaccination and infection." (PMID 35215119, 2022). "There is increased release of the cytokines TNF, IL-1a, IL-1β, IL-2, and IFN-γ, as well as the recruitment of virus-specific T- and B-lymphocytes, accompanied by cellular and humoral antibodies to resist the infection." (PMID 35479306, 2022). "The major cellular players during the early phase of infection are macrophages and DCs, as professional antigen-presenting cells and sources of IL-12, but also NK cells, ILC1, NKT cells and γδT cells, as sources of IFN-γ and TNF-α." (PMID 35203386, 2022). "We emphasize that most patients had a history of trauma, tattoos, electromagnetic girdle, or anti-TNF-α biological drugs, while three patients did not have information on the origin of the infection." (PMID 36558733, 2022). "TNFα, on the other hand, is crucial for survival in primary and secondary infection, but GSI did not alter the production of this cytokine in lungs." (PMID 35603470, 2022). "Moreover, the experimental infection resulted in increased LZM, as well as enhanced levels of inflammatory factors, including IL-1β, IL-6, TNF-α and IL-10 in serum, indicating activation of inflammatory response following E. coli inoculation." (PMID 36198724, 2022). "Generally, in the acute phase of infection, proinflammatory cytokines that include IFN-γ, tumor necrosis factor-alpha (TNF-α), IL-1β, and IL-12 are related to parasite control, and anti-inflammatory cytokines (IL-10, IL-4, and transforming growth factor-beta [TGF-β]) result in opposing actions." (PMID 36389843, 2022). "TNF-α, which is secreted by macrophages, dendritic cells, and T cells, plays a major protective role against MTI and transmits signals regulating immune cell migration to the infection sites and the formation of microbicidal granulomas." (PMID 35189895, 2022). "Additionally, after infection with three PRV strains, the transcriptional levels of IL-1β, IL-6, TNF-α, and IFN-β were highest at 3 h, 6 h, 9 h, and 12 h, respectively, and then gradually decreased." (PMID 35458442, 2022). "Inflammation is associated with the release of proinflammatory cytokines, such as tumor necrosis factor α (TNF‐α), interleukin 1 (IL‐1), and interleukin 6 (IL‐6), which aid in the recruitment of immune cells (such as neutrophils) to the site of injury or infection." (PMID 35315122, 2022). "It would be of interest to investigate whether TNF induces prosurvival NF-κB and MAPK-dependent signaling in the studied infection models." (PMID 35844510, 2022). "We tested the serum samples for classical inflammatory and anti-inflammatory cytokines as systemic markers for a prolonged immune response, and observed a trend for slightly elevated cytokine levels for IL8, TNFα, IL6, IL12p70, IL10, IL5 and IL4 in the first four months after the infection." (PMID 36293090, 2022). "Recent work by Zheng and colleagues provided genetic evidence that the TLR2 pathway contributes to overwhelming production of inflammatory cytokines (particularly TNF-α, IL-6 and IFN-γ) during infection by SARS-CoV-2 and other β-coronaviruses, following recognition of the E protein." (PMID 35632741, 2022). "In our study there was an important increase in pro-inflammatory cytokines (IL1β, IL6, TNFα, IL18, IL23) upon infection in all the groups analyzed in comparison with age-related control samples, as also seen for the immunoregulatory cytokines IL10 and IL17A, and for Th1 IFNγ NLF." (PMID 36561744, 2022). "Bacterial burdens were significantly increased in anti-TNF-α-treated mouse organs at D8, but not at D3 of infection." (PMID 35479068, 2022). "In the setting of infection by the SARS-CoV-2 virus, it was reported quite early that hospitalized and ICU patients were producing a “cytokine storm”, including the cytokines interleukin-1α (IL-1α) and tumor necrosis factor alpha (TNF-α)." (PMID 34723652, 2022).
infection (continued). "In addition, mice treated with anti-C5aR Ab had lower serum concentrations of ALT and inflammatory cytokines, especially TNF-α and IL-6, 48 hrs after MHV-3 infection, consistent with our prior observations made by administrating C3aR antagonist." (PMID 35573780, 2022). "Infection is more likely to disseminate in immunocompromised patients, including people with AIDS; those receiving chemotherapy, organ transplants, or immunomodulatory biologics (e.g., anti-TNF and anti–IL-6); or women in the third trimester of pregnancy." (PMID 36166305, 2022). "High expression of TNF-α in these cell types was also reported in DENV and ZIKV infections." (PMID 36466642, 2022). "Interleukins (IL) IL-1, IL-4, IL-5, IL-6, TNF-α and IFN-γ are among the more commonly measured pro-inflammatory mediators (KE1496) and recruit inflammatory cells, such as macrophages and leukocytes, to the site of infection (KE1497)." (PMID 35956081, 2022). "TNF-α is part of the group of Th1 profile cytokines, which act synergistically with IFN-γ in macrophages to increase NO production, which, in turn, destroys the parasites at the beginning of the infection." (PMID 35097133, 2022). "In contrast, DPPIV and TNF-α were increased in patients and decreased in in vitro HRMC infection." (PMID 35458553, 2022). "We, therefore, quantified SC mRNA levels encoding various pro-inflammatory and disease resolving factors, namely, the monocyte chemoattractant CCL2, TNF, IFNγ, a prominent mediator of MHV virus control, iNOS, IL10 and arginase 1 (Arg1) over the course of infection." (PMID 36333761, 2022). "IL-1β, TNF-α, IFN-γ, and IL-6 plasma levels were measured on d2, d4, d6, and d8 post-infection." (PMID 36456548, 2022). "IL-10 and IFNγ CD4+ cells are important for a chronic, nonresolving infection status, and together with the elevated TNFα and IL-6 expression, these data fit well with the enhanced and prolonged inflammation in the colons of AOM/DSS-treated CerS4 LCK/Cre mice." (PMID 35163788, 2022). "Here, we observed that the production of inflammatory TNF-α and IL-1β and anti-inflammatory IL-10 was not changed following infection with Δnmo2 and Δnmo5 in contrast to infection with the wild-type strain." (PMID 35887491, 2022). "During the initial stages of infection, mice display a Th1 immune response by producing high levels of Th1 cytokines (e.g., IFN-γ, interleukin (IL) -12, TNF-α), which may participate in protection against Schistosoma infection." (PMID 35584107, 2022). "During the initial steps of infections with MEL and MSL, mycobacteria were able to evade the oxidative mechanisms of the innate immune response (ROS production by macrophages) and stimulate a pro-inflammatory environment (TNF-α, IL-1β, and IL-8)." (PMID 35873160, 2022). "Cytokines in the brain (TNF-α, CCL-2, CXCL-2, CXCL-10, IL-1β, IL-6, IL-17, and M-CSF) were upregulated after infection at 3 dpi, and the cytokine content gradually decreased with extension of the infection time." (PMID 36352407, 2022). "Similar to H37Ra infection, we found that AM failed to produce cytokines, including IL-12p40, IL-6 and IL-10, but not TNFα, in response to H37Rv infection." (PMID 36776396, 2022). "Overall, the results indicate that Omp16 did not affect IFN-γ, TNF-α and IL-4 secretion during infection by B. suis." (PMID 34675138, 2022). "The downregulation of TNF-α, NF–κB, IFN-α, IL-6, IL-12 and RANTES observed in treated H3N2 cells suggests that C1q treatment induces an anti-inflammatory state in A549 cells during the early stages of infection." (PMID 35328462, 2022). "The cytokines TNF-α, IL-6, IL-18, IFN-β, IFN-γ, and CSF3 produced by macrophages play important roles in the protection again pathogens by promoting phagocytosis and mediating the recruitment and activation of effector immune cells into the site of infection." (PMID 37431006, 2022). "ST infection also showed an increased trend for TLR4 (P = 0.099) and TNF-α (P = 0.096) mRNA levels." (PMID 36221113, 2022).
infection (continued). "Cervical secretions from women with HPV persistence (and therefore cervicovaginal dysbiosis) have upregulated IL-6, TNF-α and immunosuppressive cells compared to women with transient or an absence of infection." (PMID 36303679, 2022). "We observed that there was a significantly higher level of IL-12 and IFNγ at 7 d.p.i. upon i.p. infection and nominally, but non-significantly, higher expression of TNF and IL-1β." (PMID 35898505, 2022). "Temporal analysis of inflammatory cytokine induction revealed that while SARS-CoV-2 infection of parental THP1/PMA cells did not result in induction of pro-inflammatory responses, infection of CD169+ THP1/PMA cells led to rapid induction of IL-6, TNFα, IL-1β, and IFNλ1 mRNA expression." (PMID 36279285, 2022). "Increased serum cytokine level of TNF-α and MCP-1 was observed in mice treated with M4N or ZIL while a lower IFN-γ level in ZIL-treated mice and a higher IL-12 serum level in DPI-treated mice were observed at 7 d post-infection." (PMID 36039381, 2022). "On the other hand, TNF-α had a concentration of 1.9 pg/mL at 12 h post-infection, without there being a significant increase." (PMID 35628694, 2022). "The PBS and LacAC4A groups had strong inflammation expression, showing serious infection, while the expression of inflammation in the Cip group was weakened and there was almost no expression of TNF-α and IL-6 in the Cip@LacAC4A group." (PMID 36270992, 2022). "induced significant TNF-α production during primary or secondary infection, with TNF-α being higher in negative controls." (PMID 36032120, 2022). "Furthermore, TNF-alpha production is high in HIV patients undergoing antiretroviral treatment and tends to increase as the infection progresses." (PMID 36359281, 2022). "The host's immune system releases a number of proinflammatory molecules during the blood infection stage in response to the parasite's presence, including IL-1, IL-6, IL-8, IL-12 (p70), IFN-γ, and TNF, all of which play a key role in limiting the parasite's growth and removal." (PMID 36510199, 2022). "Levels of proinflammatory cytokines in Mtb-infected lung lysates, including IL-6 and TNF, were significantly upregulated, while IL-10 levels in the coinfected group were comparable with those in the Mtb-infected group at 7 days post LCMV Arm infection." (PMID 35672321, 2022). "The results show that the secretion levels of IL-1β and IL-6 from the BALF and serum of Nlrp6−/− mice were significantly lower than those of WT mice after infection, while the secretion levels of TNF-α did not change." (PMID 36224650, 2022). "We observed a similar pattern for genes related to cytokines, TNF signaling, antigen processing and presentation, and cell adhesion molecules, with early expression of these gene sets after LASV infection and late expression after MOPV infection." (PMID 35337059, 2022). "During the peri-implantation period, γδ T cells could express TNF-α and IFN-γ, two common pro-inflammatory cytokines, which may exhibit anti-infection activity against foreign antigens in pregnancy." (PMID 36699469, 2022). "After synthesizing the data, we conclude that anti-TNF-α de-escalation in patients treated according to the label does not reduce the occurrence of infections and skin manifestation compared to patients who continued standard dosing." (PMID 35625771, 2022). "In addition, VV-IL-37-GFP infection significantly increased the levels of IL2, IFN, and TNF in HCC mice." (PMID 36146619, 2022). "First, SC were infected with ONNV at a multiplicity of infection (MOI) 1, 10−1, 10−2, and 10−3 or stimulated with the viral analog PIC 10 μg/mL, ATP 1 mM, TGF-β2 10 ng/mL, or the proinflammatory cytokines IL-1β 10 ng/mL and TNF-α 10 ng/mL." (PMID 36611893, 2022). "Upon RSV-immunization and subsequent infection, increased Vγ4+ γδ-T cells were found in mouse lungs and could produce several pro-inflammatory cytokines, including IFN-γ, TNF, IL-4, and IL-5, upon ex vivo stimulation." (PMID 36305904, 2022).
infection (continued). "Our data showed no increase in circulating TNF levels in LP 3% mice upon infection, and, although we have not measured IL-13 levels, studies demonstrated that the level of this cytokine is lower in the absence of IL-4." (PMID 33815321, 2021). "Bx795 abolished the induction of type-I/III IFNs, CXCL10, and TNF due to PVSRIPO infection; induction of IL-1β, IL-6, and IL-10 was not affected." (PMID 33767151, 2021). "In contrast to those results, but in line with our present findings, artificial infection with S. aureus did not appear to affect the mRNA levels of TNFα and IL-8 in cow MSC, and the IL-8 and TNFα levels were low or undetectable in milk." (PMID 34663465, 2021). "Untreated animals showed elevated levels of IL-6 and IL-10 but not IL-1β and TNF-α, in their lungs 4 days after the infection." (PMID 34648602, 2021). "During infection by Gram-negative bacteria, the production of TNF-α, LTs and mouse MCPT-6 participated in neutrophil chemoattraction." (PMID 34211473, 2021). "Moreover, 12 patients transferring to the ICU had higher concentrations of infection-related biomarkers (ESR, IL2R, IL6, IP10, PCT, SF, CRP, TNFα)." (PMID 33542448, 2021). "The results showed that secondary infection of SS after PRRSV infection resulted in an additive effect of CCL4, CCL14, CCL20, and IL-15, with significant synergistic upregulation of IL-6, CCL5, and TNF-α." (PMID 34513970, 2021). "At early time points, Fpr2-/- mice showed a significant decrease in CXCL1, CXCL2, IL-1β, CCL2, GM-CSF, IL-6, and CCL3 levels at 1 hour and 3 hours after infection, and an increase in IL-22 and IL-23, but there is no change in TNF-α, as compared with WT mice." (PMID 34899755, 2021). "While TNF-α and IL-1β were both produced during the early stages of infection, neither was dependent on TNC (P = 0.74 and P = 0.75, respectively)." (PMID 34319124, 2021). "On the other hand, a similar study noted that moDCs produce IFN-α, IFN-β, TNF-α, IL-6, IL-8, IL-10 and IL-1β after infection with live, but not UV-inactivated SARS-CoV-2." (PMID 33498725, 2021). "The suppression of TNF-α and IL-1β production undoubtedly promoted the ability of Lm NTSN to evade the direct bacteria-killing of macrophages, thus contributing to its survival during the early stage of infection." (PMID 35223532, 2021). "In contrast to IFN-γ expression, there was a mild, but not significant trend of increasing TNF-α gene expression from 30 to 270-days post-infection." (PMID 34026898, 2021). "Our findings in serum support and expand on this, as nearly every cytokine and chemokine involved with a cell-mediated response (MIP-2, MIP-3α, MCP-1, IL-1β, IP-10, TNF-α) was significantly elevated in the CF mouse, even without detectable infection." (PMID 34475490, 2021). "In this study, we found that vaccination-trained immune response produces heightened TNF-α, but not IL-6 and IL-1β, when encountered with the infection." (PMID 34544549, 2021). "TNF-α and IFN-γ mRNA levels increased by ~ 750-fold in the brain by day 5 after infection." (PMID 33477869, 2021). "After the infection with GTP viruses (GTPV) and PPR viruses (PPRV), cytokines such as TNF-α, IL-1β, IL-6, IL-10, IFN-α, and IFN-β might regulate their replication in vitro." (PMID 33827620, 2021). "In corroboration, the absence of intact TNF signaling did not alter the phenotype induced by the acute phase of the infection, with similar parasite burden and inflammatory status of livers and lungs of both groups of mice." (PMID 35071042, 2021). "During blood-stage infection, in response to the presence of the parasite, the host's immune system produces proinflammatory cytokines including IL-6, IL-8, IFN-γ, and TNF, cytokines which play a pivotal role in controlling the growth of the parasite and its elimination." (PMID 34790829, 2021). "Cytokines (IL-1β, IL-12, TNF-α, and IFN-γ) were quantified in sera 15 days after infection." (PMID 34336720, 2021).